LTAP1 (lipid transport auxiliary protein 1)
Description:
Required for the formation of endoplasmic reticulum-plasma membrane junctions and functions as an accessory protein for bridge-like lipid transfer protein BLTP1, participating in lipid delivery between endoplasmic reticulum and cell membranes. Regulates the phagocytosis of Gram-negative bacteria like L. pneumophila and E. coli, as well as Gram-positive bacteria such as S. aureus.
Synonyms: C1orf43; NICE3; NS5ATP4; HSPC012; NICE-3; DKFZp586G1722; S863-3
Tractability: Antibody: UniProt predicts a signal peptide or a membrane-spanning region. PROTAC: ubiquitination databases record sites on it; its protein half-life has been measured.
Gene: Protein-coding gene on chromosome 1 (154,206,668 to 154,220,681, reverse strand). Ensembl gene ENSG00000143612.
Subcellular location: Cell membrane; Golgi apparatus; Mitochondrion; Endoplasmic reticulum membrane
Subcellular location (Human Protein Atlas): Mitochondria; Cytosol
Gene Ontology:
Biological process: phagocytosis
Cellular component: endoplasmic reticulum membrane; endoplasmic reticulum-plasma membrane contact site; Golgi apparatus; mitochondrion; plasma membrane
Genetic constraint (gnomAD): Loss-of-function variants: 17 observed, 26.9 expected, observed/expected ratio (o/e) 0.63, 90% interval 0.43 to 0.95. The upper end of that interval is the gene's LOEUF score, 0.95, which puts it in group 4 of 6, group 1 being the genes least tolerant of losing a copy. Missense variants: 257 observed, 292.24 expected, observed/expected ratio (o/e) 0.88, 90% interval 0.79 to 0.98. Synonymous variants: 116 observed, 114 expected, observed/expected ratio (o/e) 1.02, 90% interval 0.87 to 1.19.
Homologues: Orthologues: chimpanzee C1H1orf43 (99% identical), pig C1orf43 (98% identical), guinea pig C1orf43 (96% identical), mouse 4933434E20Rik (96% identical), rat Ns5atp4 (96% identical), dog C1orf43 (85% identical), rabbit C1orf43 (85% identical), rat Ns5atp4-ps3 (85% identical), macaque C1H1orf43 (83% identical), tropical clawed frog c8h1orf43 (69% identical), zebrafish C16H1orf43 (60% identical), Drosophila melanogaster CG6665 (32% identical).
Diseases named in the same sentence as LTAP1 in open-access papers:
LTAP1 is named in the same sentence as 3 diseases in open-access papers, as found by Europe PMC text mining. Sharing a sentence is not in itself a finding about the gene and the disease. The quoted sentences say what the papers report.
infection (2 papers, 2021 to 2022). The state of being infected such as from the introduction of a foreign agent such as serum, vaccine, antigenic substance or organism. "In our previous study, a redox-related gene, LtAP1, from the fungus was significantly upregulated in peach shoots throughout infection." (PMID 34630367, 2021). "In our previous study, the LtAP1 gene was consistently and highly expressed in the infection stage of L. theobromae on peach shoots, implying that LtAP1 may play a crucial role in the pathogenicity of L. theobromae." (PMID 34630367, 2021). "We found that LtAP1 was a key regulator of oxidative stress response, acting in activating fungal glutaredoxin and thioredoxin systems, and suppressing plant defense responses during infection." (PMID 34630367, 2021). "Furthermore, we tested whether LtAP1 was involved in the regulation of ROS production during infection." (PMID 34630367, 2021).
LTAP1 also shares sentences with these, for which no sentence is quoted: breast carcinoma (1 paper); tumor (1).